CXCL8 (C-X-C motif chemokine ligand 8)
Diseases named in the same sentence as CXCL8 in open-access papers (continued):
Sharing a sentence is not in itself a finding about the gene and the disease.
asthma (continued). "Furthermore, we show that the histone acetylation binding BET proteins are critical to CXCL8 expression and that BET protein inhibitors offer a novel therapeutic option for modulating CXCL8 in asthma and potentially other neutrophilic diseases." (PMID 25713319, 2015). "Here we investigated chromatin modifications at the CXCL8 promoter in ASM cells from nonasthmatic and asthmatic donors to further understand how CXCL8 is dysregulated in asthma." (PMID 25713319, 2015). "In addition, neutrophil numbers and neutrophil inflammatory mediators such as CXCL8, NE, and MMP-9 are elevated in the airways of patients with severe asthma and these levels correlate with disease severity." (PMID 26663987, 2015). "JQ1/SGCBD01 and I-BET762 inhibited FCS+TGF-β-induced ASM cell proliferation and IL-6 and CXCL8 release in healthy individuals (≥ 30 nm) and in nonsevere and severe asthma patients (≥100 nm), with the latter requiring higher concentrations of these mimics." (PMID 25697361, 2015). "A higher concentration of both JQ1/SGCBD01 and I-BET762 was needed to inhibit proliferation and IL-6 and CXCL8 release from cells from patients with asthma compared with nonasthmatic subjects." (PMID 25697361, 2015). "Thus, in contrast to the Type 2 (T2 or eosinophilic) type of asthma which was mediated by IL-4, IL-5, and IL-13, the profile of the inflammatory mediators with high levels of IL-6, CXCL8, and IFNγ after TLR stimulation mirrored that of the non-T2 endotype of asthma." (PMID 39614276, 2024). "The induction of chemokines CCL20 and IL–8/CXCL8 by GCs was previously reported in human macrophages, enhanced CCL20 expression was reported in GC-insensitive neutrophilic airway inflammation in asthma and elevated CCL20 expression was found in keratinocytes in GC-exacerbated skin conditions." (PMID 39744635, 2024). "An in vitro model of NTHi infection in alveolar macrophages from COPD patients or healthy controls demonstrated NTHi induced steroid-resistant production of CXCL8, suggesting NTHi-induced inflammatory signaling in macrophages may contribute to steroid insensitivity in COPD and asthma." (PMID 37180449, 2023). "As IL-8/CXCL8 is a potent chemoattractant of neutrophil and airway neutrophilia is correlated with asthma severity, DCLK1 involvement in the thrombin-stimulated IL-8/CXCL8 expression pathway indicates that DCLK1 might serve as a new biological marker of severe asthma." (PMID 36369000, 2022). "CXCL8 levels were found to be elevated in patients' induced sputum, fuelling speculations about the potential therapeutic benefit of CXCR inhibition in severe asthma." (PMID 36164329, 2022). "However, IL-8/CXCL8 and thrombin expression in lung tissues of patients with mild asthma was not significantly different from that in the normal subjects." (PMID 36369000, 2022). "However, reduced levels of miR-146a were found irrespective of asthma phenotype, but the neutrophil chemoattractant CXCL8 and CXCL1 were only increased in the neutrophilic asthma phenotype." (PMID 33255348, 2020). "The levels of these PAHs were correlated with asthma-related biomarkers including immunoglobulin E (IgE), resistin, granulocyte–macrophage colony-stimulating factor (GMCSF) and interferon gamma (IFN-γ) as well as the cytokines; interleukin (IL)-4, IL-5, IL-8 (CXCL8) and IL-10." (PMID 33187512, 2020). "In addition, peripheral blood neutrophils from patients with severe asthma showed higher NETs than those from non-severe patients following in vitro CXCL8/ IL-8 stimulation, and NETs and neutrophil cytoplasts were positively correlated with IL-17 levels and biased toward Th17 differentiation." (PMID 34692717, 2021). "Among those, CXCL8 (IL-8), secreted by T lymphocytes, epithelial cells, smooth muscle cells, and macrophages might especially be important, as CXCL8 (IL-8) is also increased in the airways of patients with some respiratory diseases such as CF, COPD, and asthma." (PMID 23401702, 2013).
asthma (continued). "Here we assessed chromatin modifications and DNA methylation levels at the CXCL8 promoter in ASM cells isolated from individuals with and without asthma and explored the potential for BET protein inhibitors as modulators of aberrant CXCL8 expression." (PMID 25713319, 2015).
gastric cancer (321 papers, 1999 to 2026). A primary or metastatic malignant neoplasm involving the stomach. "CXCL8, which is primarily secreted by macrophages in gastric cancer, is linked to poor clinical outcomes and tumor progression." (PMID 38041130, 2023). "Previous data from gastric cancer models have shown that CXCL8 specifically derived from CAFs was implicated in driving resistance to chemotherapy." (PMID 35879507, 2022). "In gastric cancer, tumour-associated macrophages autonomously express PD-L1 by secreting CXCL8, thus promoting immune evasion." (PMID 35468838, 2022). "The chemokine IL8/CXCL8 (in block 5) deserves a more careful inspection, as some of its SNPs have been associated, although disputably, to risk of gastric cancer." (PMID 33503840, 2021). "A high serum CXCL8 level was associated with poor response to cisplatin therapy in gastric cancer patients." (PMID 35011369, 2021). "Aberrant activation of CXCL8 in cancer-associated fibroblasts is correlated with poorer survival in gastric cancer patients." (PMID 34126961, 2021). "Aberrant chemokine CXCL1 and CXCL8 expression in CAFs was closely associated with tumor progression and poorer survival in gastric cancer patients." (PMID 35011369, 2021). "As low-dose CXCL8 was reported to induce the migration and invasion of human gastric cancer cell lines, we suspected that even a low expression level of CXCL8 would be associated with tumor progression." (PMID 29285315, 2017). "Similarly, we also see an induction of high CXCL8 by TNFα, which promotes neutrophil migration into the TME, and is thought to promote tumour progression and CXCL8 expressing CAFs are associated poor prognosis in gastric cancer." (PMID 39743376, 2025). "IL-1β induces gastric cancer by blocking the production of gastric acid, causing epigenetic changes, stimulating angiogenesis, attracting adhesive factors, and releasing other inflammatory factors, such as interleukin-8 (IL-8/CXCL8)." (PMID 39950099, 2024). "In addition, CXCL-8 is linked to gastric cancer proliferation; it promotes chronic inflammation and propagates infection." (PMID 38572314, 2024). "In addition, previous studies discovered that low expression of CXCL8 is associated with unfavorable prognosis in gastric cancer, and the same phenomenon is also observed in the present study." (PMID 35265130, 2022). "Previously studies indicated that the single nucleotide polymorphism (SNPs) of CXCL8 gene were significantly associated with increased risk or progression of non small cell lung cancer, gastric cancer, differentiated thyroid cancer and ovarian cancer, especially CXCL8-251 A/T." (PMID 35372515, 2022). "Similarly, CXCL-1 and CXCL-8 positivity in CAFs was significantly associated with poor prognosis in gastric cancer patients, whereas CXCL-8,−10, and−11 CAFs expression correlated with resistance to neoadjuvant CT and poor prognosis in BC." (PMID 33553157, 2020). "In studies of OV and gastric cancer, overexpression of CXCL8 promotes the proliferation, migration, invasion, EMT, and angiogenesis of tumor cells, thereby accelerating peritoneal metastasis." (PMID 41461671, 2025). "CAF-derived CXCL8 (also known as IL-8) can promote tumour resistance to cisplatin in gastric cancer." (PMID 39780187, 2025). "In gastric cancers, loss of PTPRD induced CXCL8 and promoted angiogenic and metastatic events, via STAT3 and ERK signalling pathways." (PMID 40871563, 2025). "Human IL-8 (CXCL8) is particularly relevant as it is significantly upregulated in gastric cancer tissues and correlates with tumor invasion, metastasis, and angiogenesis, while also serving as a neutrophil chemoattractant in chronic gastritis." (PMID 40673273, 2025). "Gastric cancers have been shown to have higher levels of CXCL8, while renal cell carcinomas have been shown to have higher levels of CXCL1/3/5/8, which enhances angiogenesis and tumorigenesis." (PMID 38515019, 2024).
gastric cancer (continued). "In fact, CXCL-8 levels positively correlate to poor clinical outcomes for patients who have gastric cancer, decreasing CD8+ T cell infiltration and increasing immunosuppressor programmed death ligand 1 (PD-L1) expression on macrophages." (PMID 38572314, 2024). "STAT1 transcription factor leads to the overexpression of IL‐10 that induces the immunosuppressive phenotype of TAMs and continues the overexpression of CXCL8 in a positive feedback loop aiding in the invasion and proliferation of gastric cancer cells." (PMID 38703051, 2024). "In gastric cancers, the loss of PTPRD induced CXCL8 and promoted angiogenic and metastatic events via the STAT3 and ERK signalling pathways." (PMID 38339334, 2024). "Hypoxia promotes gastric cancer progression by activating the release of CXCL8 by macrophages and the CXCL8/CXCR1/2-JAK/STAT1 pathway." (PMID 39199574, 2024). "This pathway directly promotes the expression of gastric cancer-derived IL-10 and forms a positive feedback loop that further releases macrophage-derived CXCL8 under the IL-10/NF-κB/CXCL8 axis." (PMID 39199574, 2024). "At the same time, CXCL8 derived from gastric cancer have the ability to activate endothelial cells in cancer vessels, promote angiogenesis." (PMID 37377954, 2023). "CXCL8 is an important pro-cancer inflammatory factor in TME which overexpressed in gastric cancer, ovarian cancer, colorectal cancer, breast cancer, and prostate cancer." (PMID 37377954, 2023). "In the early 2000s, researchers found that CXCL8 plays a significant role in gastric cancer pathogenesis." (PMID 36831112, 2023). "In gastric cancer (GC), CXCL8 secreted by macrophages contributes to the immunosuppressive ecosystem by inducing CD274 macrophages." (PMID 37898619, 2023). "Activation of CXCR2 by CXCL1 and CXCL8 stimulates the proliferation of transformed cells, which leads to gastric cancer." (PMID 37408240, 2023). "CXCL8 plays a key role in the inflammation process, and certain studies suggested that inflammation is part of innate immunity; moreover, CXCL8 promotes immune evasion by inducing the expression of PD-L1 in gastric cancer, as previous studies reported." (PMID 36532065, 2022). "Multiple studies have suggested that CXCL8 can induce PD-L1 + macrophages to promote the immunosuppressive microenvironment in gastric cancer." (PMID 36295640, 2022). "For various cancers, serum CXCL8 is a potential biomarker, such as for gastric cancer, pancreatic cancer, colorectal cancer, and non-small-cell lung cancer." (PMID 36295640, 2022). "In analogy to our results, the AUC values of CXCL8 were superior to those obtained for classical tumor markers (for BC—CA 15-3, for gastric cancer—CEA and CA 19.9)." (PMID 36431173, 2022). "In gastric cancer, TAMs promote PD-L1 expression through the secretion of CXCL8, thereby suppressing the antitumor effects of CD8+ T cells." (PMID 36467074, 2022). "Further, a recent report indicates a novel subtype of MDSCs that attract by CXCL8 in human gastric cancer." (PMID 35372515, 2022). "It was reported that inactivated PTPRD in gastric cancer can promote angiogenesis by inducing CXCL8 expression." (PMID 36248841, 2022). "H. pylori infection up-regulates CXCL8 expression through down-regulating KLF4 expression in gastric cancer cells and thus facilitates the recruitment of MDSCs, thereby shaping an immunosuppressive microenvironment." (PMID 35795038, 2022). "In the present study, we found that EBV upregulated CXCL8 expression, and CXCL8 significantly promoted vasculogenic mimicry (VM) formation of gastric carcinoma (GC) cells." (PMID 35321317, 2022). "MEK/ERK and transcription factors AP-1 and NFκB are all involved in CXCL8 upregulation by IL-1β in gastric-carcinoma cells and by CD40 in human fetal microglia." (PMID 35806457, 2022). "The high expression of CXCL8 is significantly associated with decreased CD8+ and Ki67+ T cells infiltration and unfavorable clinical outcome in gastric cancer patients." (PMID 34729112, 2021).
gastric cancer (continued). "Scholars have found that CXCL8 is a key chemokine for gastric cancer metastasis, which is mainly derived from TAM." (PMID 34729112, 2021). "In gastric cancer tissues of chemoresistant patients, CXCL8 was highly expressed and located in CAFs by immunohistochemistry assay." (PMID 35011369, 2021). "IL-6/CXCL8 induces MDSC arginase I production to suppress CD8+ T-cell activity through the PI3K-Akt signaling pathway in gastric cancer." (PMID 35011369, 2021). "CXCL8 signaling axis also plays an indispensable role in colorectal carcinoma, renal cell carcinoma, pancreatic cancer, thyroid tumors, gastric cancer, and lymphomas." (PMID 34126961, 2021). "CXCL8 enhances proliferation and migration through metadherin in gastric cancer in a xenografted mice model." (PMID 35011369, 2021). "Microarray analysis revealed that protein tyrosine phosphatase receptor delta-inactivation-induced CXCL8 promotes angiogenesis and metastasis in gastric cancer." (PMID 34126961, 2021). "For example, CXCL8, whose source was in gastric cancer-derived MSCs, has induced the expression of PD-L1 in gastric cancer cells." (PMID 32582148, 2020). "For example, in gastric cancer CSF-2 elevated the production by macrophages of CXCL8, which then elevated PD-1 expression by TAMs, giving rise to inhibition of CD8+ T cell activities." (PMID 32582148, 2020). "Clinically, aberrant activation of CXCL1 and CXCL8 in CAFs correlated with poorer survival in gastric cancer patients." (PMID 31147602, 2019). "In Jurkat lymphoma and human gastric cancer cell line, activation of CXCL8 is mediated through cooperative action of AP-1 and NF-κB." (PMID 29147073, 2017). "High expression of migration-related factors, such as cyclooxygenase 2 (COX-2), Vascular endothelial growth factor (VEGF), CXC chemokine ligand (CXCL)-8, chemokine (C-X-C motif) receptor (CXCR)-2, and CXCL-1, are associated with gastric cancer progression." (PMID 22479608, 2012). "Earlier studies by our group have shown that SPARC, CLIC1, SLPI, CXCL1, CXCL8, and CXCR2 are highly expressed and associated with advanced stages and poor prognosis of gastric cancer." (PMID 22479608, 2012). "The blockade of CXCL8 using the neutralizing antibody inhibited M2 polarization of macrophages induced by gastric cancer-derived mesenchymal stromal cells (GC-MSCs) and GC-MSC-primed macrophages notably improved the migratory and invasive abilities of SC cells." (PMID 39007996, 2024). "Hypoxia also triggers the secretion of CXCL8 in TAMs that activates the C‐X‐C Motif Chemokine Receptor 1/2 (CXCR1/2) on the plasma membrane of gastric cancer cells further activating the Janus kinase 1/Signal transducer and activator of transcription 1 (JAK/STAT1) signaling pathway." (PMID 38703051, 2024). "A study found that PTPRD inactivation promotes tumor metastasis by induced CXCL8 in gastric cancer." (PMID 37602864, 2023). "Interestingly, analyses performed in gastric cancer patients showed that CXCL8 has higher SP values than the routine marker (CA 19-9)." (PMID 36431173, 2022). "In the analysis of transcriptome data from hypoxic and normoxic cultured human peripheral blood mononuclear cell (PBMC)-derived macrophages, it was found that C-X-C motif chemokine ligand 8 (CXCL8) expression was increased, and CXCL8 is reportedly involved in gastric cancer malignancy." (PMID 36613819, 2022). "Hence, effective inhibition and blockade of CXCL8 and disruption of the immunosuppressive microenvironment are of importance for improving the effects of immunotherapy in gastric cancer." (PMID 35795038, 2022). "CXCL8 inhibitors may drive antitumor response, providing potential therapeutic effects for patients with gastric cancer." (PMID 34126961, 2021). "CXCL8 derived from tumor-associated macrophages is associated with decreased CD8+ T cell infiltration and inhibits its function by inducing the expression of PD-L1 on macrophages, which indicates poor prognosis in gastric cancer patients." (PMID 32632106, 2020).